SLC7A11 (solute carrier family 7 member 11)
Diseases named in the same sentence as SLC7A11 in open-access papers (continued):
Sharing a sentence is not in itself a finding about the gene and the disease.
Sjögren’s syndrome (1 paper, 2025). "In the realm of natural compounds, recent studies have revealed that apigenin modulates Sjögren’s syndrome-induced ferroptosis in salivary gland epithelial cells through the ERα signaling-mediated ATF3/SLC7A11 axis." (PMID 40934008, 2025).
skin melanoma (1 paper, 2019). "Our work thus motivates further studies to elucidate the potential link between BAP1 and SLC7A11 in human skin melanoma." (PMID 31780644, 2019).
sporotrichosis (1 paper, 2024). The commonest and least serious of the deep mycoses, characterized by nodular lesions of the cutaneous and subcutaneous tissues. "The results showed that compared with the control group, the expressions of DKK1 and ACTG2 were significantly downregulated while the expressions of JAK3 and SLC7A11 were significantly upregulated in the tissues of the sporotrichosis patients, consistent with the sequencing data." (PMID 38172590, 2024).
staphylococcus aureus infection (1 paper, 2022). An infectious process in which the bacteria Staphylococcus aureus is present. "KEGG assays indicated that high expression of SLC7A11 might participate in the modulation of intestinal immune network for IgA generation and Staphylococcus aureus infection." (PMID 35509981, 2022).
Telangiectasia (1 paper, 2023). Telangiectasias refer to small dilated blood vessels located near the surface of the skin or mucous membranes, measuring between 0.5 and 1 millimeter in diameter. "We also noted that RT can not only restrict GSH synthesis by activating the ataxia-telangiectasia mutated gene to inhibit SLC7A11 of glutamate-cystine antiporter Xc- but also induce ferroptosis by inducing the expression of ROS and ACSL4." (PMID 37007068, 2023).
testicular tumours (1 paper, 2021). "At immunohistochemistry (IHC) the evaluation of a pilot subset of primary testicular tumours, revealed that CCDC6 staining inversely correlated with the xCT/SLC7A11 expression levels, supporting our in vitro evidence." (PMID 34841108, 2021).
tumor suppressor (1 paper, 2024).
vitiligo (1 paper, 2022). Generalized well circumscribed patches of leukoderma that are generally distributed over symmetric body locations and is due to autoimmune destruction of melanocytes. "Interestingly, IFN-γ exposure did not significantly reduce the expression of GPX4, SLC7A11, or SLC3A2, implying that other factors are involved in the increasing ferroptosis-sensitive state of melanocytes in patients with vitiligo." (PMID 35962439, 2022).
Waldenstrom macroglobulinemia (1 paper, 2024). "Increased expression of glutamate-cysteine ligase catalytic subunit (GCLC) and solute carrier family 7 member 11 (SLC7A11) can regulate GSH metabolism, promote GSH synthesis, and markedly increase the proliferation of Waldenstrom macroglobulinemia cells." (PMID 39091635, 2024).
tumor (1,021 papers, 2010 to 2026). "In parallel, CD8+ T-cell-derived interferon-γ promotes ferroptosis by suppressing SLC7A11-mediated cystine uptake, while tumour-associated macrophages buffer oxidative stress through iron sequestration and glutathione-dependent antioxidant programs." (PMID 42226605, 2026). "Molecular mechanistic studies confirm that SLC7A11‐deficient tumor models display heightened sensitivity to PD‐L1 monoclonal antibody therapy and its combination with radiotherapy." (PMID 40919133, 2025). "In patients with cancer, reduced expression of SLC3A2/SLC7A11 in tumor tissues is associated with a “T-cell inflamed” phenotype." (PMID 40693608, 2025). "Increasing evidence supports frequent overexpression of SLC7A11 in various human cancers, with its upregulation being causally linked to the development and progression of different types of tumours or cancers." (PMID 39354653, 2025). "They found that inhibiting SLC7A11 can reduce the generation of cancer-associated fibroblasts (CAFs), thereby decreasing tumor invasiveness and resistance." (PMID 40012016, 2025). "Specifically, overexpression of SLC7A11 is associated with tumor stage, lymph node metastasis, and chemotherapy resistance." (PMID 39917300, 2025). "Further mechanistic studies, such as SLC7A11 knockdown in immune cell–tumor co-cultures, are warranted to validate these associations." (PMID 40978058, 2025). "A pan-cancer analysis across The Cancer Genome Atlas (TCGA) datasets was performed to investigate SLC7A11 genetic alterations, its impact on the tumor microenvironment (TME), tumor mutation burden (TMB), and therapy response." (PMID 40978058, 2025). "Pancancer data from the TCGA database clearly demonstrate that higher SLC7A11 expression in tumor tissues is associated with shorter overall survival of cancer patients (P < 1.0E-15)." (PMID 39569390, 2025). "In GBM, cells have a high demand for iron to promote tumor growth and progression, so these cells are susceptible to ferroptosis, of which SLC7A11 (solute carrier family 7 member 11) is a key antagonist." (PMID 40847302, 2025). "SLC7A11 is highly expressed in various cancers, including EC, and its expression is associated with tumor microsatellite instability and central carbon metabolism." (PMID 41313521, 2025). "Studies have shown that overexpression of SLC7A11 is closely associated with tumor cell resistance to chemotherapy and radiotherapy." (PMID 40012016, 2025). "Conversely, SLC7A11 upregulation enhances cellular resistance to ferroptosis, a mechanism implicated in tumor chemoresistance." (PMID 40735482, 2025). "IFN-γ, which is secreted by CD8+ T cells, can downregulate the expression of the Xc− system (which includes SLC7A11) in tumor cells, making them more susceptible to ferroptosis." (PMID 41514908, 2025). "Conversely, inhibition or loss of SLC7A11 has been demonstrated to impede tumour growth and metastasis." (PMID 39354653, 2025). "By inhibiting glucose transporters, cancer cells with overexpressed SLC7A11 can cause this disulfide reaction, which inhibits tumor cell growth." (PMID 40299524, 2025). "This is particularly relevant for cancers characterized by high expression of SLC7A11, which is closely associated with tumor immune escape due to its role in promoting cell survival and antioxidant defense." (PMID 40012016, 2025). "This suggests that overexpression of SLC7A11 promotes tumor progression and is associated with a poor prognosis." (PMID 38534739, 2024). "Expression levels of DRGs, especially SLC7A11, were significantly elevated in tumor samples compared to normal samples, which was associated with poorer outcomes." (PMID 38397869, 2024). "Growing evidence indicates that SLC7A11 is significantly upregulated in various malignancies and is closely associated with tumor metabolism." (PMID 38994627, 2024). "High SLC7A11 expression has been associated with tumor metabolism, which is highly dependent on glutamine and glucose for nutrient supply." (PMID 39769017, 2024).
tumor (continued). "IFN-γ released by CD8+ T cells down-regulates the expression of two subunits of system Xc-, SLC3A2 and SLC7A11, inhibits the uptake of cystine by tumor cells, enhances lipid peroxidation, causes ferroptosis of tumor cells, and releases DAMP." (PMID 39359721, 2024). "SLC7A11 is implicated in tumor development through its regulation of redox homeostasis, amino acid metabolism, modulation of immune function, and induction of programmed cell death, among other processes relevant to tumorigenesis." (PMID 39040097, 2024). "The upregulation of SLC7A11 induces the infiltration of tumor-associated macrophages (TAMs) and MDSCs by activating the colony-stimulating factor 1 (CSF1)/colony-stimulating factor 1 receptor (CSF1R) axis." (PMID 38397901, 2024). "Dysregulation of redox homeostasis, often associated with aberrant GSH metabolism and SLC7A11 activity, contributes to various pathologies, including cancer, where SLC7A11 overexpression promotes tumor survival by enhancing resistance to oxidative stress." (PMID 39532848, 2024). "Prior studies have revealed the significantly upregulated expression of SLC7A11 in tumor-associated macrophages (TAM)." (PMID 38397869, 2024). "In tumor cells with high expression levels of SLC7A11, glucose deficiency induces a large accumulation of disulfide bonds, which leads to abnormal disulfide bond cross-linking and contraction of actin cytoskeletal proteins." (PMID 38277541, 2024). "Cysteine can also enter tumor cells from the microenvironment via the sodium-independent cystine/glutamate antiporter, which is known as an xc– system or xCT encoded by the SLC7A11 gene." (PMID 39125992, 2024). "In concordance with our study, it was demonstrated that high SLC7A11 expression was significantly associated with the tumor growth type in CCA." (PMID 39335604, 2024). "Phosphatase and tensin homolog deleted on chromosome 10 (PTEN), one of the most frequently mutated tumor suppressors in cancer, also plays a critical role in modulating SLC7A11 expression." (PMID 39534872, 2024). "Recent research highlights the pivotal role of SLC7A11-mediated redox status in various aspects of tumor growth, including multidrug resistance, tumor-associated disulfidptosis, and iron-dependent cell death." (PMID 38504986, 2024). "SLC7A11 expression was significantly associated with the tumor grade, initial tumor site, and N stage." (PMID 39350768, 2024). "IL-1β-induced excessive cystine transport protein-SLC7A11 enhances the expression of PD-L1 and colony-stimulating factor 1, and promotes tumor-associated macrophage and MDSC infiltration, therefore leading to HCC metastasis." (PMID 38466483, 2024). "The elevated SLC7A11 expression associated with PTEN loss is thought to confer a survival advantage to tumor cells by enhancing their antioxidant defenses, thereby promoting tumorigenesis and resistance to therapy." (PMID 39534872, 2024). "There was a significant association between high SLC7A11 expression and the tumor growth type (p = 0.01)." (PMID 39335604, 2024). "Recently discovered disulfidptosis, a novel form of cell death, is closely associated with aberrant tumor glucose metabolism, particularly in tumors with elevated SLC7A11 expression." (PMID 38504986, 2024). "High SLC7A11 mRNA and SLC7A11 protein expression were significantly associated with high tumor grade (p ≤ .02), indicating a potential role in cancer progression." (PMID 38073087, 2024).
tumor (continued). "Subsequent investigations revealed that elevated levels of the SLC7A11 protein unexpectedly heightened the susceptibility of tumor cells to oxidative stressors, leading to increased rates of tumor cell apoptosis." (PMID 39040097, 2024). "SLC7A11 expression was tightly associated with various immune cell infiltration disorders in the ACC tumour microenvironment (TME)." (PMID 37919768, 2023). "The result indicated that the expression of SLC7A11 was statistically significant associated with tumor stage (OR = 1.77, 95% CI [1.10–2.86], P = 0.02, I2 = 61%, random-effect model)." (PMID 36874967, 2023). "Our study demonstrated that high SLC7A11 expression is associated with worse prognosis in patients with cancer and more advanced tumor stage." (PMID 36874967, 2023). "We also performed a correlation analysis for SLC7A11 and tumour mutation burden (TMB), which showed a positive correlation between SLC7A11 and TMB (cor = 0.33, P = 0.004)." (PMID 37919768, 2023). "Specifically, SLC7A11 upregulation in tumor cells was demonstrated to be associated with increased resistance to temozolomide or cisplatin chemotherapy treatments." (PMID 37298344, 2023). "As BAP1 is frequently mutated in human cancers, BAP1 mutation contributes to tumor development by abrogating its ability to suppress the SLC7A11 expression and induce ferroptosis." (PMID 36552652, 2022). "Cancer-associated fibroblasts (CAFs) are highly dependent on SLC7A11 for protection from exogenous oxidative stress, and support pancreatic ductal adenocarcinoma tumour growth and intratumoural fibrosis." (PMID 35804831, 2022). "In the transgenic mouse model of gastric cancer, when CD44v was knocked out, the tumor growth was suppressed, and there was a significant loss of the SLC7A11 gene." (PMID 35566360, 2022). "Recent studies revealed that selenium enrichment in tumor is closely associated with the elevated expression of SLC7A11, supporting an important role of SLC7A11 in the selenophilic properties of cancer cells." (PMID 35053507, 2022).
tumor (continued). "Another study showed that RT in combination with imidazole ketone erastin (IKE) or sorafenib (both of which are class I FINs inhibiting SLC7A11 activity) caused dramatic tumor suppression in both CDXs and PDXs." (PMID 33891303, 2021). "Further, upregulation of the cystine transporter xCT (encoded by SLC7A11) in BhomoKA compared to KA neoplasms suggests a potential role for ferroptosis deregulation in the tumor-promoting phenotype induced by BAP1 loss." (PMID 34830866, 2021). "Our data revealed that SLC7A11 expression had an association with tumor size (chi-square test, P = 0.009), smoking history (chi-square test, P = 0.010), lymph node metastasis (chi-square test, P = 0.009), and TNM stage (chi-square test, P = 0.013)." (PMID 34722314, 2021). "Of note, our results showed that ATP5MC3, CDKN1A, and SLC7A11 expression was dramatically positively related with the tumor mutational burden (TMB) score in EC." (PMID 34531924, 2021). "In the PDAC mouse model, deletion of the gene encoding a subunit of system Xc- (Slc7a11) in established tumors substantially increased median survival and even caused complete tumor regression in one mouse." (PMID 33670230, 2021). "Cancer-associated BAP1 mutants lose their abilities to repress SLC7A11, leading to attenuation of ferroptosis and tumor promotion." (PMID 34830866, 2021). "While little is known about the function of Fam117b, Slc7a11 downregulation is associated with RT-induced ferroptosis in tumor cells." (PMID 34364390, 2021). "Applying RNA sequencing analysis in renal CAKI1 tumor cells to explore highly upregulated molecular signatures in response to hLcn-2, we identified a cluster of genes (SLC7A11, GCLM, GLS), which are implicated in regulating ferroptosis." (PMID 34069743, 2021). "Higher level of SLC7A11 has been detected in several types of human cancer, and inhibition of SLC7A11 would render tumour cells susceptible to ferroptosis." (PMID 34609072, 2021). "In terms of cancer metabolism, the tumor suppressor BRCA1-associated protein-1 (BAP1) inhibits SLC7A11 expression in a de-ubiquitin-dependent manner, resulting in lipid peroxidation and ferroptosis." (PMID 33330074, 2020). "STAT1 deficiency in tumor cells abolishes the IFN-γ-mediated downregulation of SLC7A11 and reverses RSL3-induced lipid peroxidation and cell death." (PMID 32778143, 2020). "Reduced levels of SLC7A11 expression caused by the p533KR variant in xenograft tumor models lead to an apparent depression of tumor growth." (PMID 30450337, 2018). "It is expelled out of tumor cells in exchange for cysteine through the antiporter xCT (also known as system Xc-, encoded by SLC7a11 in humans)." (PMID 25228443, 2014).